LRRC3C (leucine rich repeat containing 3C)
Tractability: Antibody: UniProt predicts a signal peptide or a membrane-spanning region; its Gene Ontology location is reachable by antibodies, with medium confidence.
Gene: Protein-coding gene on chromosome 17 (39,927,732 to 39,944,999, forward strand). Ensembl gene ENSG00000204913.
Subcellular location: Membrane
Gene Ontology:
Molecular function: signaling receptor activity
Cellular component: plasma membrane; membrane
Genetic constraint (gnomAD): Loss-of-function variants: 15 observed, 17.12 expected, observed/expected ratio (o/e) 0.88, 90% interval 0.58 to 1.35. The upper end of that interval is the gene's LOEUF score, 1.35, which puts it in group 5 of 6, group 1 being the genes least tolerant of losing a copy. Missense variants: 353 observed, 363.26 expected, observed/expected ratio (o/e) 0.97, 90% interval 0.89 to 1.06. Synonymous variants: 149 observed, 160.39 expected, observed/expected ratio (o/e) 0.93, 90% interval 0.81 to 1.06.
Homologues: Orthologues: chimpanzee LRRC3C (99% identical), macaque LRRC3C (93% identical), dog LRRC3C (87% identical), rabbit LRRC3C (85% identical), pig LRRC3C (82% identical), rat Lrrc3c (81% identical), guinea pig LRRC3C (79% identical), mouse Lrrc3c (78% identical). Paralogues in human: LRRC3 (35% identical), LRRC3B (33% identical), VASN (26% identical), TLR5 (19% identical), TLR7 (19% identical), IGFALS (19% identical), LRRC32 (19% identical), NRROS (18% identical), TLR6 (18% identical), TLR8 (18% identical), RXFP2 (17% identical), RXFP1 (16% identical), and 10 more.
Diseases named in the same sentence as LRRC3C in open-access papers:
LRRC3C is named in the same sentence as 6 diseases in open-access papers, as found by Europe PMC text mining. Sharing a sentence is not in itself a finding about the gene and the disease. The quoted sentences say what the papers report.
inflammatory bowel disease (2 papers, 2015 to 2024). A spectrum of small and large bowel inflammatory diseases of unknown etiology. "LRRC3C is believed to affect the risk of inflammatory bowel disease by regulating cell proliferation and apoptosis." (PMID 37950349, 2024).
asthma (1 paper, 2022). "Some genes were linked to specific asthma phenotypes, including ORMDL3/GSDMB/LRRC3C (17q21.1), which is linked with childhood asthma." (PMID 36294997, 2022).
breast carcinoma (1 paper, 2018). "The two immediate proximal genes instead, LRRC3C and GSDMA, neither interact with the mutation site nor expressed at detectable levels in either the MCF-7 breast cancer cell line or primary breast tumors (TCGA)." (PMID 30404658, 2018).
LRRC3C also shares sentences with these, for which no sentence is quoted: breast tumors (1 paper); childhood asthma (1); Crohn disease (1).